CIZ1 (CDKN1A interacting zinc finger protein 1)
Diseases named in the same sentence as CIZ1 in open-access papers (continued):
Sharing a sentence is not in itself a finding about the gene and the disease.
cancer (15 papers, 2010 to 2025). A tumor composed of atypical neoplastic, often pleomorphic cells that invade other tissues. "CIZ1 has been linked with a range of human cancers and in mice genetic deletion of CIZ1 manifests as hyperproliferative lymphoid lineages in females." (PMID 37580709, 2023). "This shows that, similar to germ-line deletion of CIZ1, interference with CIZ1 assemblies in an acute setting can significantly alter gene expression across the genome, including genes linked with cellular plasticity and cancer." (PMID 40067149, 2025). "CIZ1-associated pathologies are not limited to cancer, however." (PMID 35289833, 2022). "We previously designed an exon-junction microarray that identified a number of novel variants of CIZ1, including one common cancer-associated CIZ1-variant characterized by a continuous deletion of part of exon 8, exon 9–11 and part of exon 12, here referred to as CIZ1-F." (PMID 30280956, 2018). "Dysregulation of CIZ1 protein may mediate the disruption of DNA replication and impair the genetic fidelity of genomic DNA, which can contribute to gene mutations and cancer development." (PMID 26861296, 2016). "Here, we describe the aberrant expression of CIZ1 in human cancers and model the effects of destabilizing protein fragments on RNA–protein assemblies and underlying chromatin." (PMID 40067149, 2025). "Normally around 80% of female cells (cycling, mouse or human, primary or established non-cancer lines) contain a discrete compact CIZ1–Xi assembly." (PMID 40067149, 2025). "In vitro studies indicate that overexpression of CIZ1 leads to increased proliferation, migration, invasion, colony formation, and tumor growth in dozens of cancer cell lines." (PMID 26861296, 2016). "In each case, there is a cancer-specific alteration resulting in increased Ciz1 protein levels or alternative splicing of Ciz1 transcript." (PMID 28036012, 2016). "Deregulation of Ciz1 transcript and protein levels are required for proliferation, invasiveness and anchorage-independent growth in cancer cell lines in vitro." (PMID 28036012, 2016). "Consistent with CIZ1, several cell cycle regulators that can interact with CIZ1 are also involved in pathology of these cancers." (PMID 26861296, 2016). "This review will describe the function of Ciz1 in maintenance of genome integrity by regulation of the G1/S transition and evaluate its role in cancer biology." (PMID 28036012, 2016). "CDK2, which can phosphorylates CIZ1 on T174, T222 and T323, is rarely found to be genetically or epigenetically altered in cancers." (PMID 26861296, 2016). "A number of NM proteins (for example, RUNX, CIZ1 and cyclin E) have been reported to have an altered localization in cancer cells, sometimes due to failure to be recruited to the NM." (PMID 23134523, 2013). "Depletion of Ciz1 from normal and cancer cells restrains entry to S phase and inhibits cell proliferation." (PMID 20831784, 2010). "Using a pair of paediatric cancer cell lines and a pool of eight normal lines as reference, the array identified expected and novel CIZ1 splicing events." (PMID 20831784, 2010). "Potential relevance to the earliest, pre-mutation, stages of cancer aetiology focussed our analysis on the immediate response of CIZ1-null cells to the quiescence triggers, rather than the downstream events or resulting lineages." (PMID 37580709, 2023). "In support of the second possibility, non-variant epitopes of CIZ1 are consistently detected in plasma from people with or without cancer indicating that presence in the blood is part of normal CIZ1 biology." (PMID 27867087, 2017). "Taken together, the data suggest that, in vivo, the cancer-specific epitope is composed of a relatively short fragment of CIZ1 encompassing the exon14b/15 junction, mounted on fibrinogen alpha chain, which itself makes up most of the mass of the 65–70 kDa species." (PMID 27867087, 2017).
cancer (continued). "Some variants have been associated with a range of proliferative disorders including cancers, suggesting that deregulation of normal CIZ1 function might negatively impact on identity." (PMID 27934662, 2017). "Ciz1 was found to directly associate with the oncogenic transcription factor Yes associated protein 1 (YAP) and promote higher order interactions with Tafazzin (TAZ) and TEA Domain Transcription Factor 1 (TEAD) that are commonly activated in cancer." (PMID 28036012, 2016). "We propose that Ciz1 may contribute to oncogenesis by induction of DNA replication stress and that Ciz1 may be a multifaceted target in cancer therapy." (PMID 28036012, 2016). "Collectively, these studies suggest that CIZ1 is an important regulator of cancer genesis and growth, and targeting CIZ1 might interrupt oncogenic signaling pathways." (PMID 26861296, 2016). "Though several alternative splicing variants of CIZ1 mRNA have been found to be associated with cancer development, no mutations of Ciz1 gene have been found to be responsible for cancer genesis." (PMID 26861296, 2016). "The dependence on continued expression of Ciz1 for tumor growth and other cancer-specific characteristics suggest that Ciz1 may be a multifaceted target in cancer therapy." (PMID 28036012, 2016). "Another possibility for the involvement of CIZ1 in cancer development may be due is its roles in DNA replication." (PMID 26861296, 2016). "Importantly, targeting cancer-specific splice variations or depletion of Ciz1 by siRNA reduced tumor growth in xenograft models, identifying a potentially selective therapeutic avenue to reduce tumor proliferation." (PMID 28036012, 2016). "Taken together, evidence supports the view that some cancers display gene addiction for Ciz1, or that Ciz1 may be a driver of tumor growth in common tumor types." (PMID 28036012, 2016). "Overexpression of CIZ1 has been found in many kinds of cancer specimens and cell lines." (PMID 26861296, 2016). "In addition, Ciz1 contributes to cell cycle regulation, spermatogenesis and possibly cancer biology through direct interactions with cyclin A1/A2 that correlate with Ciz1 function in DNA replication and DNA repair respectively." (PMID 28036012, 2016). "Finally, the emerging role for Ciz1 in cancer biology is discussed." (PMID 28036012, 2016). "These CIZ1 gene expression inhibitors might become potential drugs for cancer therapy." (PMID 26861296, 2016). "Crucially, this precedes the emergence of phenotypically transformed lineages, suggesting that the epigenetic instability experienced in the absence of CIZ1 could be a driver of genome instability and possibly therefore an early (pre-mutation) driver of cancer initiation." (PMID 37580709, 2023). "Based on present studies, we speculate that CIZ1 might cooperate with cyclin E, cyclin A, p21Cip1/Waf1, CDC6, or CDK2 in cancer genesis or growth, and further studies are needed to confirm this viewpoint." (PMID 26861296, 2016). "Thus, at least one form of the CIZ1 protein is present in the circulatory system in cancer and non-cancer plasma samples alike, suggesting it to be part of normal physiology." (PMID 27867087, 2017). "Thus, CIZ1 may be more likely to be an executor rather than an oncoprotein in cancer development." (PMID 26861296, 2016).
tumor (10 papers, 2012 to 2025). "Our proposal is that expression of CIZ1 DNFs drives disruption of chromatin state in the early stages of tumor development, possibly before acquisition of driver mutations, and certainly before widespread genetic instability." (PMID 40067149, 2025). "The data lead to the conclusion that disease-associated dominant-negative CIZ1 fragments (DNFs) contribute to epigenetic instability by deprotecting loci that are normally buffered by surrounding SMACs and that this plays an early role in tumor etiology by promoting epigenetic instability." (PMID 40067149, 2025). "In addition, in Ciz1 null mouse models, ablation of Ciz1 predisposes mice to viral transformation, suggesting that it may have a tumor suppressor function." (PMID 28036012, 2016). "CIZ1 can promote tumor growth and metastasis and protect cells from radiation-induced DNA damage and apoptosis." (PMID 33184261, 2020). "Ciz1 is overexpressed in common tumors and tumor growth is dependent on Ciz1 expression, suggesting that Ciz1 is a driver of tumor growth." (PMID 28036012, 2016). "Several studies reveal that CIZ1 is involved in signaling pathways that contribute to tumor genesis and development." (PMID 26861296, 2016). "Ciz1 promotes tumor growth through activation of the oncogenic Int/Wingless (Wnt)/beta-catenin T cell factor (TCF) pathway that is aberrantly activated in a range of tumors." (PMID 28036012, 2016). "It was identified that the higher the stage, the higher the positive expression rate of the CIZ1 protein, suggesting that CIZ1 may promote tumor cell infiltration and metastasis." (PMID 36358661, 2022). "Furthermore, CIZ1 overexpression or mis-splicing promotes tumour cell growth and targeted depletion of CIZ1 can reduce cellular proliferation or tumour size." (PMID 33093612, 2020). "It has yet to be determined whether Ciz1 contributes to transcription regulation in normal somatic cells; but in tumor cells, Ciz1 may contribute to adaptive mechanisms to enhance oncogenic signaling." (PMID 28036012, 2016). "In addition, CIZ1 also displays tumour suppressor activity in CIZ1 ablated murine models." (PMID 33093612, 2020). "Four out of twelve smaller segments, located on chromosome 6 and 9, were isolated independently from other genomic imbalanced regions, and at least one of these regions on 9q contains tumor-related genes (NAIF1 and CIZ1)." (PMID 22551002, 2012). "For instance, CIZ1, ZNF217, ZNF281, ZKSCAN3, ZNF692, ZNF750, and ZFP36 proteins are closely related to the tumor volume, lymph node metastasis status, and TNM stage, and their expression levels had statistically significant effects on the survival time of patients with colon adenocarcinoma." (PMID 36358661, 2022). "There are currently no other reports that demonstrate that Ciz1 is commonly inactivated in tumors, whereas Ciz1 overexpression has been found to maintain tumor growth in several studies." (PMID 28036012, 2016). "Ciz1 is overexpressed in aggressive CRC tumors, which are Ciz1-dependent for tumor proliferation." (PMID 28036012, 2016). "Interestingly, the differential expression plot across tumor types also shows CIZ1 expression is not much different between tumors and their normal tissues quantitatively, unlike MCM2 for example supporting the concept of possible predisposition." (PMID 30107825, 2018). "However, complete lack of CIZ1 has also been shown to promote tumorigenesis, suggesting tumour suppressor properties." (PMID 27934662, 2017).
neurodegenerative disease (1 paper, 2022). A disorder of the central nervous system characterized by gradual and progressive loss of neural tissue and neurologic function. "In particular, CDKN1A, which together with interacting zinc finger protein 1 (CIZ1) plays a key role in DNA replication and cell cycle progression through the G1/S checkpoint, may contribute to neurodegenerative diseases." (PMID 35592696, 2022).
CIZ1 also shares sentences with these, for which no sentence is quoted: leukaemias (2 papers); lymphoma (2); medulloblastoma (2); ependymoma (1); Ewing’s Tumor (1); gallbladder tumor (1); glioma (1); hepatocellular carcinoma (1); neurological disorders (1); non-small cell lung carcinoma (1); Onset (1); Primary Torsion Dystonias (1); Torticollis (1); urinary bladder cancer (1).